BACH2 (BACH transcriptional regulator 2)
Diseases named in the same sentence as BACH2 in open-access papers (continued):
Sharing a sentence is not in itself a finding about the gene and the disease.
type 1 diabetes (17 papers, 2012 to 2025). "Another variant in BACH2 positively associated with the same immune cell traits also overlapped with increased risk for type 1 diabetes (T1D) and systemic lupus erythematosus (SLE)." (PMID 39045270, 2024). "In fact, BACH2 variants were associated with diabetes type 1 in a study of genome-wide association (GWA) genotyping and treatment with a BACH inhibitor lowered glycemia in a model of single cells of pancreatic islets from diabetes type 2 individuals." (PMID 37160609, 2023). "This association exhibits a low to moderate linkage disequilibrium (LD) with a BACH2 variant of type 1 diabetes (T1D) and Crohn’s disease." (PMID 37228820, 2023). "The type 1 diabetes-associated loci Bach2/rs11755527 were observed to be relevant to RA in Pakistani patients but with no significant relevance in British Caucasian." (PMID 32082072, 2019). "Linkage and GWAS have identified more than 50 loci associated with the risk of type 1 diabetes in the human genome, and BACH2 is one of them." (PMID 32082072, 2019). "For example, BACH2/rs3757247 is associated with childhood-onset type 1 diabetes and insulin-triggered type 1 diabetes in Japan." (PMID 32082072, 2019). "The risk allele (T‐allele) frequency of BACH2 rs3757247 in the six patients with insulin‐triggered type 1 diabetes was 0.75, and was significantly more frequent than that in 86 control Japanese participants (0.43; P = 0.0382)." (PMID 30970177, 2019). "Different SNPs of BACH2 which is associated with the genetic risk of type 1 diabetes have been found in multiple independent populations." (PMID 32082072, 2019). "In conclusion, many experiments have confirmed that Bach2 is associated with the genetic risk of type 1 diabetes." (PMID 32082072, 2019). "BACH2 variants have previously been associated with the more common autoimmune endocrinopathies, type 1 diabetes and autoimmune thyroid disease." (PMID 27680876, 2016). "Polymorphisms at BACH2 have been associated with numerous inflammatory diseases including Crohn’s disease and Type 1 diabetes." (PMID 26444573, 2015). "BACH2 has been previously associated with a spectrum of diseases with autoimmune component: type 1 diabetes, Graves' disease, celiac disease, Crohn's disease and multiple sclerosis." (PMID 23382691, 2013). "In one example, we show that a type 1 diabetes risk variant alters T cell regulatory element activity near the BACH2 gene, suggesting a possible mechanism for how this variant may affect disease." (PMID 37289818, 2023). "BACH2 has been implicated as a type 1 diabetes risk factor by GWAS, and may have a role in response to viral antigens." (PMID 22957057, 2012). "At the 6q15 locus associated with type 1 diabetes, in line with previous reports, variant rs72928038 was a naïve CD4+ T cell caQTL linked to BACH2 and we validated the allelic effects of this variant on regulatory activity in Jurkat T cells." (PMID 37289818, 2023). "The findings reported herein show that BACH2 rs3757247 was significantly more frequent in the six patients with insulin‐triggered type 1 diabetes than in non‐diabetic control participants and type 2 diabetes patients with or without insulin treatment." (PMID 30970177, 2019). "This is supported by a recent study which showed that variants in LD with SH2B3, BACH2, and PTPN22 are associated with TPOAb levels in patients with type 1 diabetes." (PMID 24586183, 2014). "Gene polymorphisms of the single gene locus encoding Bach2 are also correlated with a variety of immune-mediated diseases including multiple sclerosis (MS), RA, CP, type 2 chronic airway inflammation, inflammatory bowel disease (IBD), and type 1 diabetes." (PMID 32082072, 2019). "The T allele frequency of BACH2 in the six patients with insulin‐triggered type 1 diabetes (0.75) was found to be significantly higher than that in non‐diabetic control participants and type 2 diabetes patients with and without insulin treatment (P = 0.035, 0.034 and 0.037, respectively)." (PMID 30970177, 2019).
type 1 diabetes (continued). "Genetic variations within Bach2 locus are associated with numerous immune-mediated diseases including multiple sclerosis (MS), rheumatoid arthritis (RA), chronic pancreatitis (CP), type 2 chronic airway inflammation, inflammatory bowel disease (IBD), and type 1 diabetes." (PMID 32082072, 2019). "As the variant of BACH2 could have a slightly altered Tregs function, it could not make an adjustment for the derangement of insulin‐specific autoreactive T cells in the periphery, resulting in the development of insulin‐triggered type 1 diabetes." (PMID 30970177, 2019).
Immunodeficiency (13 papers, 2018 to 2025). Failure of the immune system to protect the body adequately from infection, due to the absence or insufficiency of some component process or substance. "BTB domain and CNC homolog 2 (BACH2) functions as a mediator in primary adaptive immune response and immune deficiency." (PMID 37415251, 2023). "This was consistent with previous studies which showed that mutations and loss-of-function variants of BACH2 resulted in immunodeficiency and disruption to regulatory T cell function, with subsequent autoimmunity." (PMID 32724101, 2020). "However, increased expression of FCRL3, SKAP2, and AP003774 was associated with lower risk of T1D and RA, while decreased expression of BACH2 and RPS26 increased immune disease risk." (PMID 41361473, 2025). "This work has greater implications on how pathogen-driven hemolytic events influence the adaptive immune responses of their hosts via heme modulation of B cells through degradation of BACH2, and even T cells via degradation of BACH1 and BACH2, creating immune dysfunction." (PMID 37639483, 2023).
leukemia (10 papers, 2017 to 2026). A malignant (clonal) hematologic disorder, involving hematopoietic stem cells and characterized by the presence of primitive or atypical myeloid or lymphoid cells in the bone marrow and the blood. "Through interrogation of clinical CAR products, we further found an association between BACH2 activity and clinical outcomes in patients with leukemia." (PMID 41545540, 2026). "BACH2 deficiency could cause deregulated checkpoint control signaling and lead to B-cell precursor leukemia cells." (PMID 30654767, 2019). "Here we identified a subset of high-risk leukemia characterized with high BCL6 and low BACH2 expression and associated with Ikaros dysfunction." (PMID 28030830, 2017). "In several types of leukemia and lymphoma, disruption of wild type BACH2 expression is attributed to viral integrations." (PMID 28030830, 2017). "As it was previously suggested that loss of BACH2 in both normal pre-B cells and pre-B ALL may lead to leukemia, one could expect that HO-1 would be in turn elevated in leukemic cells." (PMID 33498175, 2021). "In addition to Myc and Bcl2, other tumor-promoting genes such as Eef2 and Myh10 were upregulated in leukemia cells, whereas tumor suppressors such as Ikzf1, Ikzf2, Arid1b, Arid2, Samhd1, Bach2, and Myo18b were downregulated." (PMID 34907175, 2021). "Importantly, BCL6 and BACH2 show antagonism during early B cell development, as well as in repertoire selection and counter-selection of premalignant clones for leukemia suppression." (PMID 28030830, 2017). "BCL6 orchestrates BACH2 protein stability in leukemia and lymphoma, and the BCL6/BACH2 axis equilibrium is crucial for controlling pre-BCR checkpoint cascades." (PMID 36834692, 2023). "In leukemia and lymphoma, BCL6 orchestrates BACH2 protein stability and the balance of the BCL6/BACH2 axis is essential in regulating pre B-cell receptor checkpoint cascades." (PMID 32085659, 2020). "We assume that all three genes located between MAP3K7 and CASP8AP2 (GJA10, BACH2, MIR4464) and a variable number of adjacent genes are co-deleted in these leukemias." (PMID 29914415, 2018). "Since BACH2OE xenografts showed low leukemia burden in the BM, we then wondered whether these events are mediated by reduced CD28 and/or CD40LG levels in T-ALL cells upon BACH2 overexpression." (PMID 38233409, 2024). "However, there are no reports about BCL6/BACH2 expression in leukemia patients." (PMID 28030830, 2017). "The balance between BACH2 and BCL6 controls the pre-B cell receptor checkpoint; however, its oncogenic effect in leukemia and its clinical relevance are not yet fully clarified." (PMID 28030830, 2017).
systemic lupus erythematosus (10 papers, 2015 to 2024). An autoimmune multi-organ disease typically associated with vasculopathy and autoantibody production. "To address this possibility, we examined the titers and isotypes of anti-dsDNA Ab, a signature autoantibody for lupus, in aged Bach2-deficient mice." (PMID 31819031, 2019). "Bach2 deficiency has previously been associated with systemic lupus erythematosus (SLE), but the mechanisms through which it contributes to the development of an immune response against healthy tissue in many parts of the body were unclear." (PMID 31819031, 2019). "Furthermore, one recent GWAS meta-analysis also identified BACH2 as a susceptibility locus in Chinese lupus patients." (PMID 33013825, 2020). "To answer these questions, we first examined whether Bach2-deficient mice spontaneously generate autoimmune responses accompanied by lupus." (PMID 31819031, 2019). "Surprisingly, we found that contradicting previous reports, Bach2-deficient autoreactive B cells gave rise to plasma cells producing IgG-switched autoantibodies, and this activity was sufficient to drive renal manifestations reminiscent of lupus." (PMID 31819031, 2019). "Diminished BACH2 expression was observed in B lymphocytes from lupus patients, and transfection of BACH2 into these B cells resulted in increased apoptosis and suppressed proliferation." (PMID 33013825, 2020). "Genetic polymorphisms within the BACH2 gene locus in human are associated with numerous autoimmune and allergic diseases including asthma, vitiligo, multiple sclerosis, type I diabetes, and systemic lupus erythematosus (SLE)." (PMID 31552021, 2019). "IKZF1, HLA–DQ2A/B, and BACH2 genetic loci that affect IgG glycome composition show pleiotropy with systemic lupus erythematosus (SLE), indicating a potentially causative role of aberrant IgG glycosylation in SLE." (PMID 26200652, 2015). "These mutations result in reduced BACH2 expression and transcriptional repression of BLIMP in patient lymphoblastoid cells, reduced memory B cells, and systemic lupus erythematosus (SLE) symptoms." (PMID 38891024, 2024). "We made an intersection of the up-DPpGCs in Pla-KO1l3 with the genes for ‘systemic lupus erythematosus’ in the GWAS catalog and found three genes in common, namely, JAZF1, DOCK10, and BACH2." (PMID 38255187, 2023).
asthma (9 papers, 2018 to 2023). "It is identified that single-nucleotide polymorphisms (rs1847472 and rs10455168) of the human Bach2 gene loci are correlated with asthma risks." (PMID 35313725, 2022). "Genome-wide association studies have identified various susceptibility loci of Bach2 which are linked with Th2 inflammatory diseases such as asthma and inflammatory bowel disease." (PMID 35313725, 2022). "Genome-wide association studies have linked variations in Bach2 gene to asthma in humans, and global Bach2 deficiency in mice leads to unprovoked TH2 immunity and fatal eosinophilic crystalline pneumonia." (PMID 36033397, 2022). "Several genome wide association studies have also found significant associations between the presence of single nucleotide polymorphisms in BACH2 and susceptibility to inflammatory diseases, including rheumatoid arthritis, Crohn's disease, asthma, and multiple sclerosis." (PMID 30459773, 2018). "Since variations in the Bach2 gene have been linked to asthma in humans and Bach2 deficiency led to eosinophilic crystalline pneumonia in mice, we assessed whether Treg-specific Bach2 deficiency affected the development of fungal protease-induced allergic inflammation in the lungs." (PMID 36033397, 2022). "In summary, findings presented in this manuscript provide mechanistic insights into the role of Bach2 in regulating Treg homeostasis and protecting humans against Type 2 immunity such as asthma and other allergic disorders." (PMID 36033397, 2022). "RORA has been shown to play a role in lung development and childhood asthma and studies in mice have shown BACH2 to repress T-cell cytokine production indicating lower levels of this protein in asthma may contribute to unregulated inflammation." (PMID 35386986, 2021). "Moreover, a whole-genome sequencing association study of asthma severity in Europeans evidenced eight genome-wide significant loci previously reported as associated with asthma (IL1RL2, TSLP, HLA-DQA1, BACH2, C11orf30, RAD51B, and GSDMB) and lung function (THSD4)." (PMID 37761964, 2023). "Activation of Fhl2 by recall allergen stimuli downregulated Bach2 and JunD and activated the ERK1/2-AP1 and STAT6 pathways, inducing a memory-driven asthma phenotype." (PMID 36524132, 2022). "Expression levels of BACH2 (P = <0.0001 for both) and CD247 (P = 0.0002, vs. C and P = 0.0204 vs. MA for CD247) were significantly lower in severe asthma compared to controls and mild-moderate asthma." (PMID 35386986, 2021). "Thus, future studies on T cell BACH2 might best be directed toward disease where these CD4+ T cell subsets are more important, such as multiple sclerosis or asthma, which are Th17 and Th2 cell-dependent, respectively." (PMID 30459773, 2018).
lymphoma (9 papers, 2009 to 2025). A malignant (clonal) proliferation of B- lymphocytes or T- lymphocytes which involves the lymph nodes, bone marrow and/or extranodal sites. "Analysis of wild-type Eμ-Myc mice demonstrated that the population expressing low levels of Bach2 exhibited the earlier onset of lymphoma seen in c-rel–/– mice." (PMID 26522720, 2016). "Although Bach2 mRNA levels are uniformly low in all Eμ-Myc/c-rel–/– and c-rel+/– lymphoma samples analysed, we observed a wide range of Bach2 mRNA expression in end-stage wild-type Eμ-Myc tumours." (PMID 26522720, 2016). "BACH2 has been shown to play a critical role in oxidative stress-mediated apoptosis induced by cytotoxic agents in lymphoma cells." (PMID 23936317, 2013). "This assay showed a 134-fold higher expression level of the Bach2 transcript resulting from the alternative promoter within mesenteric lymphoma from mouse 1206, when compared to the average expression level in the other examined tumors and in normal spleen." (PMID 19159451, 2009). "Immunoblot analysis of tumor extracts confirmed that cellular proteins that are highly expressed in GC B cells, including cyclin D3, GCSAM, TCL1, Myb, TCF3 and BACH2 are expressed at higher levels in the ΔEBNA2 + Myc lymphomas in comparison to the ΔEBNA2 alone lymphomas." (PMID 38620028, 2024). "In DLBCL, the expression of PRDM1 appears to be very weak in lymphoma cells, hence the constitutive expression of BACH2 may contribute to maturation arrest of lymphoma cells, leading to lymphomagenesis." (PMID 35008187, 2021). "Interestingly, in Eμ-Myc mice RelA regulation of Bach2 was only seen in the 'end-stage' lymphomas, suggesting that c-Rel is the primary driver of Bach2 expression." (PMID 26522720, 2016). "Therefore, the consequences of NF-κB regulation of Bach2 expression may vary depending on the stage of lymphoma development." (PMID 26522720, 2016). "Therefore, wild-type mice with reduced levels of Bach2 have a very similar pattern of lymphoma onset to that seen in the c-rel–/– mice, providing a potential mechanism that allows this NF-κB subunit to function as a tumour suppressor in this model of c-Myc-driven B-cell lymphoma." (PMID 26522720, 2016). "We demonstrate that, opposite to the expected result, c-rel–/– Eμ-Myc and TCL1-Tg mice exhibit earlier onset of lymphoma and that this result can be explained by c-Rel-dependent regulation of the B-cell tumour suppressor BTB and CNC homology 2 (Bach2)." (PMID 26522720, 2016). "Of note, the P493-6 cell line expresses much lower levels of some BL-associated (and GC B cell expressed) cellular proteins in comparison to the N1, N3 and N4 stable cell lines derived from the ΔEBNA2 + Myc lymphomas, including CD10, GCSAM, BACH2, and CD179B (IGLL1)." (PMID 38620028, 2024).
celiac disease (8 papers, 2011 to 2024). An autoimmune genetic disorder with an unknown pattern of inheritance that primarily affects the digestive tract. "In an analysis of peripheral blood mononuclear cells in coeliac disease, interferon-γ and BACH2 were identified as central to the gene expression changes." (PMID 31229436, 2019). "BACH2 is a very interesting candidate gene for involvement in coeliac disease." (PMID 26444573, 2015). "Our current results place the candidate genes SH2B3, CTLA4, BACH2 and UBASH3A at the very heart of the immune response in the pathogenesis of both T1D and celiac disease." (PMID 21829393, 2011). "Lastly, four of the nine TPOA associated SNPs (in SH2B3, CTLA4, BACH2 and UBASH3A) have also been associated with celiac disease (but not the SNPs in RASGRP1, STAT4, PTPN22, IL2 and FCRL3)." (PMID 21829393, 2011).
diffuse large B-cell lymphoma (8 papers, 2009 to 2025). "In diffuse large B-cell lymphoma (DLBCL), BACH2 mutations occur in about 5% and BACH2 expression is a predictor of an inferior outcome in the DLBCL high-risk group." (PMID 35008187, 2021). "CircSPEF2, which is generated by the reverse splicing of SPEF2, is lowly expressed in diffuse large B-cell lymphoma and affects its progression through the circSPEF2-miR-16-5p-BACH2 axis." (PMID 41217541, 2025). "the expression of Bach2 was downregulated in patients with the Epstein–Barr virus (EBV)-positive subtype of diffuse large B-cell lymphoma (DLBCL)." (PMID 40128849, 2025). "Moreover, the Bach2 expression level has proven to be a useful marker to predict disease-free and overall survival of patients with diffuse large B-cell lymphoma, where a favorable prognosis is correlated with a high expression level of Bach2." (PMID 19159451, 2009). "Recently, reports have also shown that BACH2 expression level is correlated with overall disease-free survival in diffuse large B-cell lymphoma (DLBCL) patients, indicating a tumor suppressive role of BACH2." (PMID 23936317, 2013). "For instance, BACH2 has been shown to function as tumor suppressor in mantle cell lymphoma (MCL) and diffuse large B-cell lymphoma (DLBCL), whereas in another study its expression has been associated with poor prognosis in DLBCL patients." (PMID 33316777, 2020).
multiple sclerosis (8 papers, 2013 to 2025). A progressive autoimmune disorder affecting the central nervous system resulting in demyelination. "In humans, genome-wide association studies link polymorphisms in the BACH2 locus to autoimmune and inflammatory conditions." (PMID 27468266, 2016). "In a mouse model of multiple sclerosis (experimental autoimmune encephalomyelitis; EAE), Bach2 was down-regulated in Th17 cells and expression was negatively associated with disease severity." (PMID 30459773, 2018).